BMP2 (bone morphogenetic protein 2)
Diseases named in the same sentence as BMP2 in open-access papers (continued):
Sharing a sentence is not in itself a finding about the gene and the disease.
cancer (continued). "In MDA-MB 231 cancer cells, overexpression of Neogenin (a co-receptor for BMPs) significantly increased apoptosis whilst inhibiting BMP-2 induced phosphorylation of Smad1/5/8." (PMID 28733469, 2017). "Our findings suggest that BMP2 promotes cancer aggressiveness through activation of mTORC1 pathway in NPC cells." (PMID 28455969, 2017). "Bone morphogenetic protein-2 (BMP2) is a secreted protein that highly expressed in a variety of cancers and contributes to cell proliferation, migration, invasiveness, mobility, metastasis and EMT." (PMID 28455969, 2017). "Oridonin inhibited cancer growth by repressing the expression of proinflammatory mediators like IL-33 and bone morphogenetic protein-2 (BMP-2)." (PMID 26999089, 2016). "BMP-2 plays a key inhibitory role in governing the proliferation and aggressive features of human cancer cells in HCC and colorectal carcinoma." (PMID 27661009, 2016). "Three SNPs, rs2740349 (GEMIN4) in carcinoma tissue, and rs235768 (BMP2) and rs2059691 (PRKRA) in normal mucosa, were significantly associated with altered mRNA expression levels across genotypes after multiple comparison adjustment." (PMID 27107574, 2016). "When queried for the three most common BMP ligands: BMP2, 4 and 7, we observe that basal cancers have upregulation of BMP2 and BMP7 and downregulation of BMP4." (PMID 26274893, 2015). "In cancer cells, the TGFB2 and BMP2&4 ligands are implicated with promoting EMT, whereas BMP5 and BMP7 are inhibit basal and/or TGF-β-induced EMT." (PMID 25972361, 2015). "Previous results indicate that BMP-2 blocs transition of the cell cycle from the G1 to S phase, which then inhibits proliferation of several types of cancer." (PMID 25797254, 2015). "Accordingly, a group of genes that we identified by ChIP-seq and that responded differentially to GATA3 (for example, BMP2, ERBB4 and KIF16B) are linked to proliferation and maintenance of normal or cancer stem cells." (PMID 25410484, 2014). "Our data analyses showed that the relative expression levels of BMP-2 mRNA in cancer tissues (61 samples, 0.8545 ± 0.14650) were significantly higher compared to matched adjacent normal tissues (61 samples, 0.1386 ± 0.0285) (P = 0.000)." (PMID 24946687, 2014). "BMP2 plays widely roles in regulation of migration and invasion of cancer cells or osteoblast differentiation." (PMID 23284895, 2012). "Here we show that BMP-2 can be successfully expressed by E. coli and that such bacteria can kill cancer cells in a noggin-sensitive fashion, providing proof of principle for this strategy." (PMID 22315590, 2012). "The effects of BMP-2 on cancer cells are controversial and are perhaps dependent on the tissue and environment where they are expressed." (PMID 19366455, 2009). "Further investigation into combining BMP2 inhibition with other therapeutic strategies, such as immunotherapy, may provide a more comprehensive approach to improving cancer treatment outcomes." (PMID 40552583, 2025). "For instance, inhibiting BMP-2 or vimentin could sensitize cancer cells to existing therapies or prevent metastatic spread." (PMID 39859358, 2025). "Osteoinduction could be enhanced through the addition of bone morphogenetic protein 2 (BMP-2), but growth hormones have the potential to accelerate cancer growth, reinforcing the value of stress-driven osteogenesis as a safe and clinically viable approach." (PMID 41136443, 2025). "Aberrant expression of BMP2 has been reported in several cancer tissues." (PMID 39850359, 2025). "Similarly, BMP2 has been found to promote cancer growth, invasion, and migration across a variety of cancer types." (PMID 39796131, 2024). "Interestingly, enforced expression of BMP4 resulted in a trend of increased AKT1 phosphorylation in both SMAD4-expressing and SMAD4-knockdown cells, consistent with previous reports of a similar effect by BMP2 in other cancers." (PMID 38689334, 2024).
cancer (continued). "The potential predictive roles of HER2, CXCL6 and BMP2 as biomarkers in the treatment of different cancers had suggested that they may have played significant roles in cancer biology." (PMID 39741907, 2024). "On the contrary, FSTL1 suppresses the BMP2 pathway, which induces cancer cell differentiation." (PMID 38672212, 2024). "Studies have shown that BMP2 has a dual effect on tumorigenesis, which may promote or inhibit cancer progression." (PMID 38510491, 2024). "BMP2 is a growth factor and plays an important role in bone formation, but recent studies found that BMP2 might also play a role in carcinoma progression." (PMID 38468450, 2024). "The aberrant expression of BMP2 has been demonstrated to participate in the biological process of outside the skeletal system, including regulating the proliferation, differentiation, processes of cancer cells." (PMID 38059889, 2023). "Moreover, evidence has demonstrated that BMP2 is upregulated in many cancers, and is related to the progression and growth of malignant tumors including non-small-cell lung cancer, osteosarcoma, gastric cancer, and nasopharyngeal carcinoma." (PMID 38059889, 2023). "Recently, evidence has suggested that the TGF‐β and BMP2 pathways may play opposing roles in cancer." (PMID 34910361, 2022). "We anticipate that specific targeting of BMP2/4 using the VHHs could form a basis for personalised treatment in SMAD4 deficient EAC, and perhaps in other SMAD4 mutated cancers." (PMID 35902550, 2022). "However, most published studies have suggested that cells acquire ER stress by soluble factors released from cancer cells, such as BMP2." (PMID 36035215, 2022). "To examine whether BMP2 depletion reduces cancer metastasis in vivo, we used 7–8 week old NOD-SCID mice to generate a lung-to-lung orthotopic metastasis mouse model." (PMID 36175474, 2022). "For example, Yan used the Zn-based zeolitic imidazole framework (ZIF-8) as a carrier to deliver bone morphogenetic protein 2 (BMP-2) and cisplatin, thus defining different spatial distributions and environment-adaptive release patterns of osteogenic growth factors and anti-cancer drugs." (PMID 36017162, 2022). "Thus, our work finds a new potential mechanism about how BMP2 signaling functions in regulating cancer metastases." (PMID 34136487, 2021). "In the cancer microenvironment DPMSCs secrete pro-adhesive molecules, including BMP2, CX3CL1, and VEGFA, which may regulate the adhesive properties of MDA231 cells through their paracrine effect or through their secretome; this needs to be examined." (PMID 34944000, 2021). "Another mechanism to generate cancer stem cells could emerge from a “reprograming” process and results from a continuous exposure of mature cells to BMP2 and BMP4." (PMID 35047500, 2021). "In patients treated with BMP2 for spinal fusion, the risk of cancer was no greater than patients not treated with BMP2." (PMID 34200672, 2021). "However, in the present case, neither osteoblast-like cells nor pluripotent stromal cells were observed around the osseous matrix, and the carcinoma cells showed osteonectin, osteocalcin, BMP-2, TGF-β1, and Gli2 expression." (PMID 33388078, 2021). "BMP2 had been reported to be involved in the tumorigenesis and the progression of cancer." (PMID 32195173, 2020). "VEGF and BMP2 have shown to have a synergistic effect in inducing osteogenesis, angiogenesis, and metastasis, therefore, administration or inhibition of both VEGF and BMP2 was suggested as a possible strategy to enhance bone healing or decreasing the incidence of cancer metastases respectively." (PMID 33584642, 2020). "Clinical and non-clinical studies that assessed the association between BMP2 and cancers had come to conflicting conclusions." (PMID 32195173, 2020). "Moreover, in metastatic HNSCC, cancer-containing lymph nodes have been shown to express high levels of BMP (BMP2, 4 and 5), highlighting a role for the pathway in metastatic spread." (PMID 32708289, 2020).
cancer (continued). "Combined BMP2/7 and ATRA treatment by using local drug delivery approach such as BMP2/7 and ATRA loaded nanoparticles targeting bone niche might be better approach to treat both metastasized cancer and metastasis-caused osteolysis." (PMID 30159139, 2018). "Thus, BMP2 can exert varying, and even opposing, effects on cancer cells depending on type and context." (PMID 29416020, 2018). "BMP2-induced activation or inactivation of SMAD-independent signaling, especially PI3K/AKT and MAPK pathways, has been implicated in the promotion or suppression of cancer progression." (PMID 29416020, 2018). "The aberrant expression of BMP2 in above studies is correlated with the proliferation, differentiation, apoptosis, invasion and migration processes of cancer cells and thus may be regarded as an oncogene." (PMID 28455969, 2017). "In addition, a study that evaluated the association between rhBMP-2 and malignancy by reviewing 515 articles found that 43 studies indicated that BMP-2 enhances cancer growth." (PMID 27636990, 2016). "One of these three SNPs, rs2740349 (GEMIN4), was associated with altered mRNA expression in carcinoma tissue, and the two other SNPs, rs2059691 (PRKRA) and rs235768 (BMP2), were associated with altered levels of mRNA expression in normal colonic mucosa across genotypes." (PMID 27107574, 2016). "Several studies conclude that no increased cancer risk occurs when BMP-2 is used for spinal arthrodesis." (PMID 25699253, 2015). "The factors leading to heterotopic bone formation are unknown; however, recently, the role of bone morphogenetic protein-2 (BMP-2) has been suggested to both induce osseous bone formation and inhibit tumorigenicity of cancer stem cells." (PMID 26347846, 2015). "Whether the PI3K p55γ/p110α dimer indeed represents an attractive molecular target to interfere with BMP2-related cancers will require intense investigations in future." (PMID 24885555, 2014). "With the use of cancer cells either monocultured or cocultured with fibroblasts invitro, we studied the effects of BMP-2 on the invasion ability of oral squamous cell carcinoma (OSCC) cell lines and analyzed the transformation and releasing factors of these cells." (PMID 25271422, 2014). "The relationship between cancer cells and BMP-2 has been investigated in several studies." (PMID 25271422, 2014). "Interestingly, WISP1 expression is itself up-regulated by both TGF-β1 and BMP-2, suggesting a “feed forward” regulatory loop for the control of these growth factors known to be important for both bone and cancer regulation." (PMID 23977121, 2013). "Recently, several lines of evidence have revealed BMP-2 signaling in cancer cells." (PMID 23900689, 2013). "Gremlin-1 binding to cancer cells was unaffected by the presence of BMP-2, BMP-4, and BMP-7." (PMID 22514712, 2012). "However, our observations are consistent with other studies which have shown that TSA treatment increases BMP2 mRNA level in human osteoclasts and also up-regulates Notch1 expression in cancer cells resulting in growth suppression." (PMID 22022609, 2011). "Among those, we identified the known BMP-2 target genes Id1, Id3, Dlx2 and Hey1, and genes that could be functionally annotated to Wnt signaling, pathways in cancer or cytokine-cytokine receptor interaction and that have critical roles in osteogenesis." (PMID 21998639, 2011). "In cancer cells, BMP-2 was found to suppress apoptosis induced by TNFα or by serum deprivation." (PMID 19366455, 2009). "However, the role and detailed molecular mechanisms of action of BMP2 in most cancers, including LSCC, remain unclear." (PMID 38610001, 2024). "Indeed, a previous study shows that sparstolonin B reduces BMP-2 expression in cancer cells." (PMID 36613594, 2022).
cancer (continued). "Moreover, in this particular study, almond seed oil was reported to inhibit cancer cell invasiveness, by the downregulation of bone morphogenetic protein 2 (BMP-2) and β-catenin pathways, and growth, by the inhibition of Ki-67 (a marker of cell proliferation) expression." (PMID 34441570, 2021). "In addition, BMP2 could accelerate cancer growth through inducing the expansion of MDSCs in bone marrows." (PMID 32195173, 2020). "Nevertheless, the interaction between BMP2 and carcinoma development remained largely unknown." (PMID 32195173, 2020). "However, functions of BMP2 signaling in carcinoma development were controversial." (PMID 32195173, 2020). "Thus, we focused on the roles of exogenous BMP2 playing in carcinoma progression." (PMID 32195173, 2020). "Also, BMP-2, -4 and -7 have exhibited altered expression in many types of malignancies including breast, prostate, osteosarcoma, glioma, ovarian, pancreatic, lung, and other cancers." (PMID 27708551, 2016). "However, 18 studies found that BMP-2 suppresses cancer proliferation." (PMID 27636990, 2016). "Therefore, 1 ng/ml was considered to be an appropriate concentration used to evaluate the effects of rhBMP-2 on cancer cells in subsequent experiments, although the content of BMP-2 obtained from bone graft materials depends on the extraction method and time and dilution ratios." (PMID 25271422, 2014). "At an incorrect dosage, various bone-related growth factors, such as BMP-2 or TGF-β, have been demonstrated to stimulate tumors and cancers." (PMID 40140186, 2025). "The complexity of BMP-2 signaling is further emphasized by its ability to mediate CSC formation, highlighting its potentially contradictory role in cancer progression." (PMID 39859358, 2025). "Our study extends the scope of those observations to demonstrate that in addition to regulating growth factor signaling in vascular and cancer cells, DCBLD2 modulates BMP2 expression and signaling in EC and VIC." (PMID 35540096, 2022). "Several studies suggested that BMP2:rs235756 increased the production of the BMP protein and the concentration of serum ferritin levels, which promoted BMP signaling in cancer progression." (PMID 34307117, 2021). "RTKN2, NFIX, PTX3, BMP2 and LOXL2 of the ceRNA network play an important role in cancer progression." (PMID 34394080, 2021). "BMP2/7 heterodimer as an TGF-β antagonist decreased TGF-β-driven SMAD signaling and cancer cell progression." (PMID 34051847, 2021). "Bone morphogenetic protein 2 (BMP2) signaling had significant roles in diverse pathological processes, such as cancer." (PMID 32195173, 2020). "Again, to address the specificity of BMP-2 and to distinguish MBT from cancer cell-intrinsic migration mechanisms, we also performed a similar experiment using EGF to replace BMP2 and found no significant reduction of EGF-induced cell migration from CBX." (PMID 32964116, 2020). "Here, we demonstrate that EBNA1 is able to stimulate the expression of the Transforming growth factor-beta (TGFβ) superfamily member, bone morphogenic protein 2 (BMP2), with consequential activation of the BMP signalling pathway in carcinoma cell lines." (PMID 32708289, 2020). "FGF2 and CHEK4 are up-regulated while the expression of CHEK1, WT1, MDM2, BARD1, BMP2, BAMBI, and SOD2, have been reported to be down-regulated in several cancer subtypes, including CRC." (PMID 31623294, 2019). "A comparison of genome-wide methylation profiles of NHK and cSCC cell lines revealed a statistically significant difference in methylation in 361 unique genes (adjusted p-value ≤ 0.01), including known cancer drivers (MAP2K2, WNT5A, COL4A1, BMP2 and FGF7)." (PMID 31336867, 2019). "We focused on the BMP pathway as BMP2 and BMP4 regulate SC fate, maintenance and differentiation processes and contribute to cancer SC emergence, maintenance and expansion." (PMID 30262802, 2018).
cancer (continued). "Since mTOR pathway regulates proliferation, metastasis and is frequently activated in many kinds of cancers including NPC, we examined the correlation between BMP2 expression and the key substrates of mTOR signaling pathway using western blotting assay." (PMID 28455969, 2017). "However, the precise mechanism of BMP-2-induced apoptosis in cancer cells remains unclear." (PMID 25797254, 2015). "BMP2 has been shown to promote CSC differentiation in glioma and other cancers." (PMID 40277903, 2025). "Cell‐cell signaling pattern between basal cancer cells (Ca), FPCS, and TPCS revealed that while Ca‐Ca and Ca‐FPC signaling mainly comprised PGF, TGFA, and VEGFA signaling, TPCS uniquely received BMP signals (BMP2/4 and GDF5) from Ca." (PMID 38582099, 2024). "In summary, through data analysis, imaging and functional assays in in vitro and in vivo preclinical models, we demonstrated the anti-cancer effects and feasibility of selectively targeting BMP2/4 in SMAD4 negative EAC by novel anti BMP4 and BMP2/4 VHHs." (PMID 35902550, 2022). "By analyzing a previously published ChIP-seq dataset that profiled genome-wide SREBP2 binding in the HCC70 human carcinoma epithelial cell line, we found that SREBP2 binding is enriched at the promoter and the intron 1 of the BMP2 gene as well as in the promoter of the LRP2 gene." (PMID 35833708, 2022). "Furthermore, a direct link between BMP2/BMP4 binding to BMP type 1 receptors and the emergence and expansion of cancer stem cells was unveiled." (PMID 35047500, 2021). "Furthermore, BMP2, majorly derived from stroma fibroblasts, enhances bone metastases of NSCLC not only through promoting migration and invasion of cancer cells, but also through both osteolytic and osteoblastic mechanisms." (PMID 32750747, 2020). "The addition of exogenous BMP2 failed to elevate the levels of pSmad1/5/8 in EBNA1-expressing carcinoma cell lines further, suggesting that pathway activation had become saturated in these cells." (PMID 32708289, 2020). "Other genes are known to be responsible for the drug resistance phenomenon, but are not directly linked to GEM: For instance, BMP2, one of the BMP isoforms, is overexpressed in many cancer types and its role is controversial." (PMID 30979003, 2019). "Within the BMP family, BMP2 and BMP4 have emerged as key regulators of normal and cancer SCs11–13." (PMID 30262802, 2018). "Moreover, the function of BMP-2 raises the possibility of cancer promotion since BMP-2 and its receptors are highly expressed in many human cancers." (PMID 27636990, 2016). "Several clinical trials involving BMP-2 treatment have been registered, primarily for patients with fractured and degenerative disk disease, but none for cancer patients." (PMID 27293448, 2016). "In addition, BMP-2, BMP-4, and BMP-7 are frequently overexpressed in various cancers including breast and prostate." (PMID 22514712, 2012). "Immunohistochemistry revealed that cancer cells were positive for cytokeratins and vimentin to a varying degree and negative for Desmin, S-100, Osteopontin, BMP-2 or BMP-4." (PMID 19040765, 2008). "Concerning the HER2 positive carcinomas, BMP-2 emerged as a negative prognostic factor." (PMID 39859358, 2025). "It was important to note that analysis in vitro could not represent the full biological effects of BMP2 in vivo, as the interaction between BMP2 and cancer environment was more complex in vivo." (PMID 32195173, 2020). "Conversely, the absence of significant differences of BMP-2 expression between BM+ and BM− suggests that it could be involved in the early phases of cancer transformation rather than during metastatic process." (PMID 30627063, 2018). "However, osteoblastogenesis might also be altered by the SIRT1‐FoxO axis and where FoxO activation of BMP2 in anti‐cancer treatments might suggest an overlapping role in RSV‐SIRT1 induced BMP2 activation in osteoblasts also." (PMID 30125963, 2018).